MALAT1 (metastasis associated lung adenocarcinoma transcript 1)
Diseases named in the same sentence as MALAT1 in open-access papers (continued):
Sharing a sentence is not in itself a finding about the gene and the disease.
liver cancer (continued). "However, this action of MALAT1 combined with HULC was abrogated in liver cancer stem cell lines transfected with pCMV6-A-GFP-HULC plus pCMV6-A-GFP-MALAT1 plus pFGP-V-RS—TRF2 or pGFP-V-RS-GFP-HULC plus pGFP-V-RS–MALAT1 plus pcDNA-CREPT (39.5%, 41.5% vs 43.7%, respectively, P > 0.05)." (PMID 27782152, 2016). "Our team has previously utilized 68Ga-labeled MALAT1-ASOs for PET/CT imaging, achieving promising results in liver cancer LM3 cell lines and xenograft models." (PMID 40597438, 2025). "The lncRNA MALAT1 regulates the stem cell properties of liver cancer through sponging miR-375 and regulates YAP1 expression, thereby regulating the promotion of liver cancer recurrence and metastasis." (PMID 36052283, 2022). "SPSS 24.0 software was used to perform ROC curve analysis on lncRNA MALAT1 and CEUS for the diagnosis of liver cancer." (PMID 35706002, 2022). "The four lncRNAs HOTAIR1, MALAT1, MEG3 and H19 have been proved to be highly correlated with primary liver cancer." (PMID 34633988, 2021). "Intriguingly, MALAT1 combined with HULC resulted in the greater action in stable liver cancer stem cell lines transfected pCMV6-A-GFP, pCMV6-A-GFP-HULC, pCMV6-A-GFP-MALAT1, pCMV6-A-GFP-HULC plus pCMV6-A-GFP-MALAT1." (PMID 27782152, 2016). "The BrdU positive rate added up to 49.7%, 44.7%, 87.8% in HULC, MALAT1, HULC plus MALAT1 overexpressed liver cancer stem cell, as well as the BrdU positive rate was 21.6% in control (t-test, P < 0.01)." (PMID 27782152, 2016). "Intriguingly, MALAT1 combined with HULC resulted in the greater effeciency in stable liver cancer stem cell lines transfected with pCMV6-A-GFP, pCMV6-A-GFP-HULC, pCMV6-A-GFP-MALAT1, pCMV6-A-GFP-HULC plus pCMV6-A-GFP-MALAT1." (PMID 27782152, 2016). "Even though there is growing evidence of their importance, the specific connection between miR-423-5p and MALAT-1 in liver cancer has not been deeply studied yet." (PMID 41029313, 2025). "Among 4238 differentially expressed (DE) evolutionary conserved non-coding RNAs, there were 94 known, putatively conserved DE lncRNAs identified, including MALAT1, HOXA transcript at the distal tip (HOTTIP), HOX transcript antisense RNA (HOTAIR) and highly up-regulated in liver cancer lncRNA (HULC)." (PMID 33477898, 2021). "In liver cancer, both YAP and MALAT1 were highly expressed, and YAP could increase MALAT1 expression at both transcriptional and post‐transcriptional levels." (PMID 32779318, 2020). "A third group reported KO of Malat1 did not affect proliferation or cell cycle progression in human lung or liver cancer cells." (PMID 32503170, 2020). "To explore whether the oncogenic function of the MALAT1 and/or HULC is dependent on TRF2, we preformed the rescued experiment in liver cancer stem cell line." (PMID 27782152, 2016). "Together, these observations suggest MALAT1, HULC and TRF2 were overexpressed in liver cancer tissue, and there was positively correlation among the expression of MALAT1, HULC and TRF2 in human primary liver cancer." (PMID 27782152, 2016). "To address the issue whether the MALAT1 combined with HULC influences on liver cancer stem cells malignant proliferation, we established the stable liver cancer stem lines transfected with pCMV6-A-GFP, pCMV6-A-GFP-HULC, pCMV6-A-GFP-MALAT1, pCMV6-A-GFP-HULC plus pCMV6-A-GFP-MALAT1." (PMID 27782152, 2016). "Finally, TIA1′s interaction with lncRNAs, e.g., MALAT1 and NEAT1, which display oncogenic features in HCC, likely also contributes to the tumor-suppressive effect of TIA1, since we could show that TIA1 silencing promotes NEAT1 upregulation in hepatic cancer cells." (PMID 35406476, 2022). "Conversely, our data suggested a transcriptional regulation of the Δsv-MALAT1 (but not of the FL-MALAT1) by the transcriptional co-activator YAP, as described in liver cancer." (PMID 27172249, 2016).
liver cancer (continued). "Strikingly, although HULC plus MALAT1 enhances TRF2 transcriptional activity via CREPT, CREPT overexpression could not promote growth of liver cancer stem cell after both HULC and MALAT1 were knocked down in liver cancer stem cells." (PMID 27782152, 2016).
myocardial infarction (67 papers, 2015 to 2026). Gross necrosis of the myocardium, as a result of interruption of the blood supply to the area, as in coronary thrombosis. "It has been shown that hypoxic EPC-EVs enhanced cardioprotection by targeting miR-497 through lncRNA metastasis-associated lung adenocarcinoma transcript 1 (MALAT1) in a mouse myocardial infarction model." (PMID 38840175, 2024). "MALAT-1 has been implicated in the pathogenesis of various conditions, including IA, aortic aneurysms, ischemic stroke, myocardial acute infarction, and vascular remodeling in hypertension." (PMID 38542406, 2024). "MALAT1 (metastasis-associated lung adenocarcinoma transcript 1), responsible for cardiac fibrosis following myocardial infarction, has been proven to stabilize LV function by preventing cardiomyocyte apoptosis when silenced." (PMID 39314559, 2024). "Metastasis-associated lung adenocarcinoma transcript 1 (MALAT1) was upregulated in patients with myocardial infarction." (PMID 38792427, 2024). "Malat1 deletion prevented heart regeneration in mice after myocardial infarction on postnatal day 3 associated with a decline in cardiomyocyte proliferation and reparative angiogenesis." (PMID 36883566, 2023). "In previous studies, we investigated the relationship between the MALAT1 gene polymorphism and the occurrence of the acute coronary syndrome, including myocardial infarction." (PMID 35392816, 2022). "Protective lncRNAs include DARS-AS1, MALAT1 (metastasis-associated lung adenocarcinoma transcript 1), and Miat (myocardial infarction associated transcript)." (PMID 35215236, 2022). "Single nucleotide polymorphisms (SNPs) on the two lncRNAs, ANRIL and MALAT1, can affect the prognosis of myocardial infarction (MI) patients." (PMID 33172104, 2020). "Our study aims to excavate the role of metastasis-associated lung adenocarcinoma transcript 1 (MALAT1) in myocardial infarction (MI), especially in an ischemia/reperfusion injury model and the underlying mechanism involving the MALAT1-miR144 axis." (PMID 31227612, 2019). "Our previous study showed that knockdown of long noncoding RNA (lncRNA) metastasis-associated lung adenocarcinoma transcript 1 (MALAT1) attenuated myocardial apoptosis in mouse acute myocardial infarction (AMI)." (PMID 31783925, 2019). "The effect of HBO on metastasis‐associated lung adenocarcinoma transcript 1 (MALAT1), a pro‐angiogenic long non‐coding RNA, in cardiac myocyte‐derived exosomes and acute myocardial infarction (AMI) is unknown." (PMID 32939962, 2020). "In addition, MALAT1 expression in tissues associated with myocardial infarction is upregulated and plays a vital role in cardiovascular disease." (PMID 31168355, 2019). "Several lncRNAs take part in acute myocardial infarction (eg, Novlnc6), heart failure (eg, Myosin Heavy Chain Associated RNA Transcript, Mhrt), control hypertrophy and apoptosis of cardiomyocytes, and the regulation of vascular growth and function (e.g., MALAT1)." (PMID 35047570, 2021). "In the context of myocardial infarction (MI), the release of miR-155 and MALAT1 from M1-Exos significantly reduces the angiogenic capacity of endothelial cells (ECs), exacerbating heart dysfunction in the microenvironment of myocardial infarction." (PMID 40371346, 2025). "Additionally, the MALAT1 regulation of IL-6 has had some contradictory results as well, with overexpression associated with the downregulation of IL-6 (trauma brain injury inflammation) and overexpression associated with elevated IL-6 levels (acute myocardial infarction)." (PMID 40507852, 2025). "Likun Ma group identified that MALAT1 is overexpressed in acute myocardial infarction mouse model which upregulates PTEN and promotes myocardial apoptosis by sponging miR-320." (PMID 39681821, 2024). "Inhibition of MALAT1 can increase theprotein expression level of NRF2/SLC7A11 in myocardial infarction models, bothin vitro and in vivo, while reducing ferrous ion levels andlipid peroxidation in cells." (PMID 39076494, 2024).
myocardial infarction (continued). "This stimulation is a result of lncRNA MALAT1 being transferred and binding to miR-25-3p, resulting in a decrease in both angiogenesis and the ability of the heart to regenerate after a heart attack." (PMID 39171328, 2024). "The results of their research suggested that MALAT1 increases the severity of heart fibrosis and negatively impacts the functioning of the heart after a heart attack." (PMID 39171328, 2024). "The collaborative effect of M1-BMMs-derived EVs inhibited the formation of new blood vessels and hindered the repair of damaged heart tissue following a heart attack, through the influence of the MALAT1/miR-25-3p/CDC42 axis and the MEK/ERK pathway." (PMID 39171328, 2024). "After myocardial infarction (MI), lncRNA MALAT1 sponges miR-26b, restoring mitochondrial-dependent apoptosis and ultimately attenuating the progression of ischemic cardiomyopathy." (PMID 38485860, 2024). "Recently, a cross-sectional study concluded that circulating MALAT1 (metastasis-associated lung adenocarcinoma transcript 1) and MIAT (myocardial infarction-associated transcript) were promising predictors for blood transfusion status in β-thal patients." (PMID 38165465, 2024). "In the adult mouse, Malat1 has been shown to induce cardiomyocyte apoptosis and fibrosis after myocardial infarction (MI)." (PMID 36883566, 2023). "Increased MALAT1 expression enhances cardiomyocyte apoptosis, and MALAT1 is highly expressed in patients with acute myocardial infarction." (PMID 37109540, 2023). "In the study of myocardial infarction, MALAT1 can regulate the programmed death of cardiomyocytes and mediate cardiac fibrosis of cardiac fibroblasts, thereby promoting myocardial infarction." (PMID 35392816, 2022). "It is reported that MALAT1 is increased in peripheral blood cells of patients with acute myocardial infarction or heart tissues of rat model of myocardial I/R injury." (PMID 35620576, 2022). "Several lncRNAs, namely, myocardial infarction-associated transcript (MIAT), H19, and metastasis-associated lung adenocarcinoma transcript 1 (MALAT1), have also been reported to be altered in AMI patients, but studies in this regard are still in their infancy." (PMID 34063483, 2021). "The lncRNA MALAT1 in peripheral blood cells has been implicated in left ventricular dysfunction in patients with myocardial infarction (MI) and might be associated with lipid accumulation and insulin resistance." (PMID 32765426, 2020). "Recent studies reported that a few lncRNAs, including H19, metastasis-associated lung adenocarcinoma transcript 1 (MALAT1), and myocardial infarction-associated transcript (MIAT), were involved in the pathogenesis of DCM in type 1 diabetic animals." (PMID 31653946, 2019). "The expression of MALAT1 is abnormal in heart diseases, with high levels in acute myocardial infarction patients and low levels in atherosclerotic plaques." (PMID 29631611, 2018). "In patients with acute myocardial infarction, MALAT1 is highly expressed, and down-regulation of MALAT1 can decrease cardiomyocyte apoptosis and improve left ventricular function in diabetic rats." (PMID 29631611, 2018). "This study’s findings indicate that another investigation by the same research team identified the therapeutic potential of hyperbaric oxygen-induced exosomes containing MALAT1 for myocardial infarction and further elucidated the mechanism of their combined application to enhance angiogenesis." (PMID 40994671, 2025). "The function of MALAT1 in myocardial infarction, as shown by prior research, is contentious." (PMID 40994671, 2025). "Previous studies have highlighted the role of disordered expression of lncRNA-H19 in the development of cardiovascular diseases and demonstrated that lncRNA MALAT1 regulates mitochondrial dynamics post-myocardial infarction while inhibiting myocardial apoptosis through the miR-26B-5p/Mfn1 axis." (PMID 40162308, 2025).
myocardial infarction (continued). "Consequently, MALAT1 is involved in the pathology of several cardiovascular diseases, including atherosclerosis, myocardial infarction, heart failure, and diabetic cardiomyopathies." (PMID 39172906, 2024). "Zhang and He reported that lncRNA Malat1/mmu-miR-30a/Becn1 was involved in myocardial infarction." (PMID 36718444, 2023). "Similarly, human-derived ESC-Pg-Exo under hypoxia conditions promoted myocardial infarct healing by improving CM survival and angiogenesis, primarily regulated by lncRNA MALAT1 via targeting miR-497." (PMID 35899033, 2022). "Additionally, MALAT1 has been reported to target miR-144-3p and thus contribute to apoptosis in myocardial infarction and affect cardiomyocyte apoptosis after hypoxia/reperfusion injury through modulation on miR-200a-3p/PDCD4." (PMID 36700468, 2022). "Previous references have reported that MALAT1 could target miR-144, and negatively regulate the expression of miR-144 after myocardial infarction." (PMID 34266379, 2021). "The downregulation of the lncRNA MALAT1 could significantly improve the cardiac function in acute myocardial infarction and hypoxia by inhibiting the ERK/MAPK pathway." (PMID 35071238, 2021). "In addition, a role for MALAT1 has been proposed in myocardial infarction (MI) where its expression is often upregulated." (PMID 31941147, 2020). "Two lncRNAs, myocardial infarction-associated transcript(MIAT) and metastasis-associated lung adenocarcinomatranscript 1 (MALAT1), may be involved in the pathogenesis ofcoronary artery disease (CAD)." (PMID 31188931, 2019). "For instance, in the context of myocardial infarction (MI), a study revealed that M1-BMMs-EVs played a role in inhibiting angiogenesis and MI post-MI by modulating the MALAT1/miR-25-3p/CDC42 direction." (PMID 39323624, 2024). "In addition, MALAT1 is associated with other non-cancer diseases, including myocardial infarction and hyperglycemia." (PMID 31168355, 2019). "MALAT1 expression is upregulated in patients with myocardial infarction (MI) and in cardiac tissue of diabetic rats." (PMID 29050364, 2017). "For example, MALAT1 knockout can alleviate acute myocardial infarction through the miR-320/Pten axis, and lncRNA Gas5 targets the miR-525-5p/CALM2 axis to regulate myocardial infarction." (PMID 35005241, 2021). "HBO induces the enrichment of exo-MALAT1 derived from cardiomyocytes, regulates the expression of CD31 and KLF2 through the MIR92A/KLF2 axis, and promotes cardiac angiogenesis after myocardial infarction." (PMID 34307511, 2021). "HBO‐induced exosomes from cardiac myocytes up‐regulate MALAT1 to suppress miR‐92a expression and counteract the inhibitory effect of miR‐92a on KLF2 and CD31 expression in left ventricular myocardium after myocardial infarction to enhance neovascularization." (PMID 32939962, 2020). "HBO significantly increased MALAT1 expression in cardiac myocytes and HBO‐induced MALAT1 and exosomes attenuated miR‐92a expression after myocardial infarction." (PMID 32939962, 2020). "For example, CDKN2B-AS1 (or ANRIL) and MALAT1 can be used to predict the development of left ventricular dysfunction as ANRIL was expressed at lower levels and MALAT1 expression was higher in patients with myocardial infarction than in healthy volunteers." (PMID 34940525, 2021). "In one study enrolling 414 patients with acute myocardial infarction (AMI) treated by primary percutaneous coronary intervention, levels of hypoxia inducible factor 1A antisense RNA 2, KCNQ1OT1, MALAT1 and ANRIL in peripheral blood cells were significantly altered with AMI." (PMID 32241300, 2020). "The co-administration of hyperbaric oxygen and exosomes facilitated the interaction between MALAT1 and miR-92a in rat cardiomyocytes, enhancing the release of KLF2 and the endothelial cell adhesion molecule CD31, which resulted in a substantial decrease in myocardial infarct size (p < 0.01)." (PMID 40994671, 2025).
myocardial infarction (continued). "Another study suggested that MALAT1 may function as a ceRNA to upregulate NLRC5 (nucleotide-binding and oligomerization domain-like receptor C5) by binding to miR-125b-5p in an IRI-induced acute myocardial infarction (AMI) mouse model, leading to the apoptosis of myocardial cells." (PMID 33299883, 2020). "However, to our knowledge, relationship between expression of both MALAT1 and miR-214 in PAH and heart disease (such as the acute myocardial infarction) was not comprehensively studied." (PMID 29559566, 2018).